IL33 (interleukin 33)
Diseases named in the same sentence as IL33 in open-access papers (continued):
Sharing a sentence is not in itself a finding about the gene and the disease.
infection (continued). "Considering the pleiotropic and complex nature of IL-33 and some patients with MAS induced by pathogen infection in clinical practice, we detected the expression of IL-33 and ST2 in CpG-induced MAS mice and further verified it in knockout mice." (PMID 37842289, 2023). "It has been reported that IL-33 is constitutively produced within the brain and its level increases during infection and injury." (PMID 37192971, 2023). "IL-33 and IL1RL1 are among the most highly replicated susceptibility loci for A30, and IL-33 has a known role in infection-mediated A susceptibility." (PMID 37573373, 2023). "Under conditions of cell damage or infection, IL-33 can be released into the extracellular microenvironment and functions as a proinflammatory factor." (PMID 37842289, 2023). "Conversely, in the event of cellular damage or infection, IL-33 transitions from a nuclear protein to a secreted cytokine, acting as an “alarmin,” signaling cellular distress." (PMID 37762328, 2023). "We have shown that naïve HIV/TB coinfected patients are characterized by increased plasma levels of IL-33, which is crucial for the control of both infections." (PMID 38035159, 2023). "TNF-α, IL-6, IL-8, IL-10, IL-13, and IL-33 in children with HRSV were significantly increased in severe infections compared to mild infections." (PMID 37239461, 2023). "At this late stage of infection, the peritoneal metacestodes which developed in the WT mice had a higher weight (12.1 ± 5.6 g) compared to those that developed in the IL-33−/− mice (7.7 ± 3.5 g, P ≤ 0.05)." (PMID 36786637, 2023). "We observed relatively lower mRNA expression of inflammatory cytokines (IFN-γ, TNF-α, IL-4, IL-6, IL-17A and IL-33) in BA.5 infection as compared to ancestral Wuhan-Hu-1 infection." (PMID 37704701, 2023). "IL-33 is a cytokine of the IL-1 family with pro-inflammatory and anti-inflammatory effects in response to infection." (PMID 38035159, 2023). "We observed increased macrophage apoptosis in the CA3 of Il33–/–mice with WNV-E218A infection and also in hippocampal CA1 7 DPI with ZIKV-Dakar." (PMID 37983247, 2023). "Type-2 AECs exhibited the largest increase in IL-33 expression relative to naïve mice and became the dominant IL-33-expressing cell type in infected mice, consistent with studies on infection with the nematode S. venezuelensis." (PMID 37783278, 2023). "As depicted in, TNF-α, IL-6, IL-8, IL-10, IL-13, and IL-33 in children with HRSV were significantly increased in severe infection compared to mild infection (p < 0.05)." (PMID 37239461, 2023). "To study the role of the IL-33/ST2 pathway in these infection models, we infected Il1rl1–/–, Il33–/–, and wild type congenic animals with WNV-E218, then monitored their survival." (PMID 37983247, 2023). "The current study also reported that IL-10, IL-13, and IL-33 were significantly increased in severe infection compared to mild infection in children with HBoV." (PMID 37239461, 2023). "IL-33 is a member of the Il-1 superfamily of cytokines and perform its role as an alarm signal in response to cellular damage induced by infection or injury to alert immune cells expressing the receptor." (PMID 38035159, 2023). "When infected, IL-33 levels remain similar between mouse strains throughout the course of infection." (PMID 37373379, 2023). "Previously, TRMs as a source of infection driven alarmins has only been described in the context IL-33 production by alveolar macrophages in response to respiratory viruses." (PMID 38030609, 2023). "Collectively, these data point to a dysregulation of brain macrophage activation following WNV-E218A infection in Il33–/–mice typified by altered metabolic state and upregulation of cell stress pathways, including apoptosis." (PMID 37983247, 2023). "Infection with NTHi is also associated with transcriptional upregulation of cytokines CCL2 (MCP1), TNF, IL-1β, IL-6, CXCL8 and alarmins (TSLP, IL-33 and IL-25)." (PMID 37180449, 2023).
infection (continued). "Altogether, these results showed that IL-33−/− mice had a more efficient Th1/Th17 component at later stage of infection than WT mice." (PMID 36786637, 2023). "To confirm this finding, we next performed IHC on B6/J and Il33–/–mice infected with WNV-E218A at 7 days post infection, using the macrophage marker Iba1 and terminal apoptotic marker cleaved-caspase 3 (CC3)." (PMID 37983247, 2023). "The infection of mice with Leishmania donovani has been shown to induce liver damage by the suppression of type 1 immune response through IL-33/ST2 axis." (PMID 36271450, 2022). "Type 2 alveolar epithelial cells are a major source of IL-33, amplifying the Th2 immune response and supporting prolonged and disseminated cryptococcal pneumonia in the course of experimental infection using C. neoformans." (PMID 36145419, 2022). "As shown in 7B, compared to RV-A1B infection alone, IL-33 mRNA levels were significantly increased in lung epithelial cells from mice undergoing heterologous infection." (PMID 36032072, 2022). "More importantly, IL-33 deficiency, the anti-IL-33 neutralizing antibody treatment, or ST2 deficient thymus transplantation restored T cell immune responses and more effectively controlled infection." (PMID 36371464, 2022). "These experiments provide further evidence that IL-33 influences the function of Th17 cells and that this effect is highly dependent on the target tissue of infection and type of pathogen." (PMID 36570798, 2022). "Within the CD45-EpCAM+ cells, IL-33 mRNA levels were highly increased in the lungs of mice undergoing heterologous infection." (PMID 36032072, 2022). "IL-33 production and the number of type-2 innate lymphoid cells differ greatly after RSV infection based on age: neonatal mice produce more IL-13 and IL-33 in response to infection than adult mice, as well as the number of type-2 innate lymphoid cells." (PMID 35327516, 2022). "They demonstrated that SARS-CoV-2 infection stimulates IL-33 expression in human epithelial cells as a damage consequence; indeed, IL-33 transcript levels increased in both cell lines 72 h after infection." (PMID 35327516, 2022). "In spite of this, when tested functionally this antiviral signature was insufficient to control HRV16 replication as IL-33 increased expression of ICAM1 which facilitated infection and increased viral replication in MCs." (PMID 36366528, 2022). "Heyen and colleagues (2016) demonstrated that type 2 alveolar epithelial cells were the major source of IL-33 during experimental infection using C. neoformans." (PMID 36145419, 2022). "We have shown that infection of immature mice with RV induces type 2 cytokine production and mucous metaplasia which is dependent on IL-33 and type 2 innate lymphoid cells (ILC2s) and intensified by a second heterologous RV infection." (PMID 36032072, 2022). "IL-33 also promotes the formation of neutrophil extracellular traps (NETs) in models of infection and IR." (PMID 36291105, 2022). "To this end, we sorted ST2+ ILC2 subsets from IL-33-treated mice based on their IL-18Rα expression and adoptively transferred them into Rag2−/−γc−/− mice 1 day before infection with Mtb." (PMID 35443177, 2022). "Blocking IL-33, in fact, attenuates respiratory inflammation in all phases of the infection, suppressing type-2 inflammation, restoring antiviral immunity, and increasing viral clearance." (PMID 35327516, 2022). "In summary, we demonstrate that IL-33 results in thymic involution-mediated naive T cell aging and impairs host control of severe infection." (PMID 36371464, 2022). "Taken together, these results demonstrate that IL-33 leads to thymic involution in a thymus-intrinsic manner during severe infection." (PMID 36371464, 2022). "Together, this indicated that our mouse model of infection similarly resulted in IL-33 induction as in humans." (PMID 34400793, 2022).
infection (continued). "Taken together, the murine ECM studies and human studies of the role of the IL-33/ST2 pathway in infectious processes highlight the complex interplay of this pathway in the host response to infection." (PMID 35800259, 2022). "In spite of this, IL-33 treatment increased permissiveness of MCs to HRV16 infection which, from the RNA-Seq data, we attributed to upregulation of ICAM1." (PMID 36366528, 2022). "IL-33 is an alarmin-type cytokine whose gene is overexpressed under stressful local conditions, such as an infection leading to alveolar injury or necrosis." (PMID 35888173, 2022). "IL-33 is recognized as an alarmin, an expression of cellular damage or infection, whose increased levels in epithelial and endothelial cells recall its pro-inflammatory role in respiratory diseases." (PMID 36498859, 2022). "The cytokines interleukin 33 (IL-33), thymic stromal lymphopoietin (TSLP) and IL-25 act as alarmins released due to cell damage caused by infection or other cellular stress." (PMID 36483186, 2022). "Early-life RV infection alters the macrophage response to subsequent heterologous infection, permitting enhanced IL-33 expression, ILC2 expansion and intensified airway inflammation and mucous metaplasia." (PMID 36032072, 2022). "Regarding IL-33, several studies report that this cytokine acts as an “alarm” that can be released upon tissue damage, stress, or infection, which acts as a danger signal for the immune system." (PMID 36204643, 2022). "Next, we explored the consequences of IL-33-induced thymic involution on T cell immunity during severe infection." (PMID 36371464, 2022). "Both IL-17A and IL-33 were induced after infection here, but only IL-33 is positively correlated with number of symptoms." (PMID 35479098, 2022). "As an inflammatory storm factor, IL-33 is an alarmin cytokine, which plays an important role in cell damage or infection." (PMID 36362440, 2022). "In T cell responses to LCMV, however, the IL-33–dependent phase of virus-reactive CD8+ T cell expansion begins after d4 after infection following priming and a first phase of expansion." (PMID 35503257, 2022). "At 12 h post challenge, mice that remained infected had significantly higher expression of Il33 mRNA compared to sham-challenged mice and mice that cleared the infection." (PMID 34400793, 2022). "In this study, heterologous RV infection did not stimulate IL-33 mRNA expression in CD45+F4/80+ cells; instead, infection stimulated epithelial cell mRNA expression of IL-33 which is dependent on M2a macrophages." (PMID 36032072, 2022). "IL-33 is involved in various immune and inflammatory diseases and is highly relevant to infections, transplantation, and cancer." (PMID 36291105, 2022). "ILC2s, a group of lineage negative non-antigen specific cells, produce IL-13 upon activation by the alarmin cytokines IL-25 and IL-33 during infection with helminths." (PMID 34578195, 2021). "Mechanistically, IL-33 mediates its detrimental effect by enhancing gut permeability and by limiting the induction of protective T helper 17 cells at the site of infection, thus impairing host defense mechanisms against the enteric pathogen." (PMID 33654214, 2021). "RV-C15 infection induced airway expression of IL-25, IL-33 and TSLP, innate cytokines responsible for activation of IL-5- and IL-13-producing ILC2s expansion." (PMID 33968043, 2021). "Consistent with the data obtained from IL-17A systemic application, infection with CR/IL17 limited the body weight loss and the systemic bacterial dissemination consequent to IL-33 treatment." (PMID 33654214, 2021). "(D) Cells from omenta of IL-33 GFP reporter mice were analyzed by flow cytometry at 3 days post-infection." (PMID 33929319, 2021). "Initially, to assess the influence of the IL-33/ST2 pathway on the systemic aspects throughout the infection by T. canis, the leukocyte profile and the levels of antibodies in the peripheral blood were evaluated." (PMID 34324507, 2021).
infection (continued). "Beginning at 1 dpi, IL-33 was administered i.p. every 2 days until 7 dpi, which resulted in a dose-dependent reduction in the frequency of infected cells at the site of infection and a decrease in parasite DNA in multiple tissues." (PMID 33929319, 2021). "Taken together, these and our data indicate that IL-33 and IL-17A adversely regulate the host response during infection with different intestinal bacteria." (PMID 33654214, 2021). "In contrast, mice treated with IL-33 during infection showed a substantial reduction in Reg3γ expression." (PMID 33654214, 2021). "Applying recombinant mouse IL-33 (rIL-33) 30 min before infection significantly decreased the bacterial burden in GAS-infected IL-33-KO mice, when compared with GAS-infected IL-33-KO ones." (PMID 34638904, 2021). "In our study, ST2-/- mice decreased the concentration of IL-5 and increased IL-33, IL-13 and IL-17 in the initial stage of infection, and with 63dpi in addition to IL-33 and IL-17, also increased IL-1β concentration." (PMID 34324507, 2021). "IFN-γ levels at the site of infection were increased by IL-33 treatment in ILC-sufficient Rag1−/− animals, but were unaffected in Rag2−/−; Il2rg−/− animals." (PMID 33929319, 2021). "Together, these results highlight that infection-induced release of IL-33 synergizes with IL-12 to promote ILC production of IFN-γ required for resistance to T. gondii." (PMID 33929319, 2021). "Well in line, the genetic ablation of IL-33 during CR infection resulted in enhanced expression of tight junction-related proteins." (PMID 33654214, 2021). "Studies show, for example, that the IL-33/ST2 axis is required to restore the integrity of the airway epithelium after infection of the lungs with influenza virus or after infestation with the nematode Nippostrongylus brasiliensis." (PMID 35011670, 2021). "In the present study, we found that IL-33 levels in the colon were only slightly increased following CR infection, but the expression of the IL-33-receptor ST2 was significantly enhanced in the colon of CR-infected mice." (PMID 33654214, 2021). "Our study on Caviae porcellus model experimentally infected with H. pylori showed that concentration of IL-33 increased during infection both locally in the gastric tissue and systemically." (PMID 34199843, 2021). "IL-33 and IL-17A have been separately described to play dichotomous functions in the gut depending on the infection context." (PMID 33654214, 2021). "More importantly, colonic expression of both Ocln and Tjp1 was significantly higher in these mice, pointing out the detrimental role of IL-33/ST2 signaling on gut epithelium integrity during CR infection." (PMID 33654214, 2021). "In an experimental model of MCMV infection, an increase in the expression of IL-33 was detected three days after infection." (PMID 33815404, 2021). "During infection, parasites and helminths are in close contact with epithelial cells and elicit the secretion of a copious amount of certain cytokines like IL-25, IL-33, and TSLP." (PMID 33435303, 2021). "Studies on IL-33 have demonstrated that as IL-33 is mostly secreted during necrosis which takes place as a result of trauma, infection, or tissue damage, hence, IL-33 elevation can be regarded as an alarmin." (PMID 34754275, 2021). "GATA3+ Treg cells express ST2 by which they can sense epithelial derived IL‐33, an alarmin which is produced by intestinal epithelial cells upon infection." (PMID 34369649, 2021). "Following CR infection, the upregulation of the antimicrobial peptide REG3γ in the colon was impaired by concomitant IL-33 application." (PMID 33654214, 2021). "Although the number of worm pairs tended to be higher in IL-33−/− mice during the course of infection, this difference was statistically significant only at the ninth week of infection (U = 0.5, P = 0.0065)." (PMID 33482904, 2021). "In this single infection mouse model, it was found that the protein and mRNA levels of IL-33 elevated sharply at 6 wpi." (PMID 34674752, 2021).
infection (continued). "Though we have yet to examine a role for IL-33 in the neonatal immune response to infection, we have detected both IL-13 and IL-5 within the BALF of P. murina infected BALB/c neonates." (PMID 34682248, 2021). "Infection with T. gondii promotes increased stromal cell expression of IL-33, and levels of parasite replication correlate with release of IL-33 in affected tissues." (PMID 33929319, 2021). "It was demonstrated that IL-33 treatment along with pathogen infection can significantly increase the population of RANKL-expressing T and B cells compared to pathogen infection alone." (PMID 34594237, 2021). "Together, these data suggest that IL-33 directly interferes with the generation of Th17 cells early during CR infection, which correlates with enhanced bacterial burden and severe pathology at later stage." (PMID 33654214, 2021). "To identify the immune cells that potentially react to IL-33 to cause the severe phenotype observed in our model, we next determined which ST2+ immune cells changed in frequency and number upon CR infection." (PMID 33654214, 2021). "We observed a strong ExoU-dependent alarmin production in BALFs 6 h after infection, such as IL-1 family alarmins IL1α, IL-33 or IL-36γ." (PMID 34516571, 2021). "Yet it is not clear how these data compare with our, as the authors focused on IL-33 and REG3γ at steady-state, in cell culture conditions, and at the late phase of CR infection when the bacteria are almost cleared in WT mice." (PMID 33654214, 2021). "To determine the overall impact of Tregs on the outcome of CR infection in the presence of IL-33, we next used DEREG mice in our model, which allow the specific depletion of all Foxp3+ Tregs by diphtheria toxin application." (PMID 33654214, 2021). "It was proposed that IL-1 and IL-33 generated by keratinocytes in response to infection activate MCs to produce IL-6, which in turn generate HDPs from keratinocytes resulting in the direct bacterial killing." (PMID 34248979, 2021). "Remarkably, our results show that IL-33 treatment during CR infection reduced the frequencies of IL-17A-expressing CD4+ T cells within the infected colon, and the impaired IL-17A response correlated with the uncontrolled pathogen clearance." (PMID 33654214, 2021). "In summary, our findings reveal the need of a tightly regulated balance between IL-17A and IL-33-mediated signals for the clearance of specific enteric bacterial pathogens and the control of infection-driven intestinal immunopathology." (PMID 33654214, 2021). "Following the larval migration, the next step was to analyze the influence of the IL-33/ST2 pathway in the lungs during infection, through parasitic burden, tissue and airway inflammation, and pulmonary physiology." (PMID 34324507, 2021). "Interleukin-33 (IL-33) is a nuclear cytokine that acts as an “alarmin” in response to the cellular damage induced by stress or by infection." (PMID 34639191, 2021). "In one study, anti-IL-33 treatment and TSLP receptor deficiency blocked the infection-induced expression of IL-25 in lung epithelial cells, and ex vivo treatment of ILC2 with TSLP increased their expression of IL-25 and IL-33 receptors." (PMID 33482904, 2021). "IL-33 can promote type 1 immune responses, especially in the context of chronic inflammation or infection." (PMID 35011670, 2021). "Following AXPN treatment and CDI, we found dramatic upregulation of Il33 gene expression and cytokine levels in the ceca of mice early during infection." (PMID 32156806, 2020). "Nonetheless, our results indicate that astrocytes are capable of responding to extracellular IL-33 during infection." (PMID 33108405, 2020). "The observed increased IL-25 expression and determination of intestinal protein levels of IL-25 and IL-33 during infection with G. intestinalis warrants further investigation." (PMID 32283818, 2020). "Organ damage in mice was further aggravated 48 h after infection, and IL-33 also increased organ damage at this time point." (PMID 33178181, 2020).